SFN (stratifin)
Diseases named in the same sentence as SFN in open-access papers (continued):
Sharing a sentence is not in itself a finding about the gene and the disease.
neurological disease (1 paper, 2019). "SFN is located at the center of an interaction network of proteins including HYAL2, NBEA, NBR1, AURKAIP1, RALGPS2, and SLC1A2, some of which have known involvement in brain function and neurological disease." (PMID 31029150, 2019).
SFN also shares sentences with these, for which no sentence is quoted: benign breast disease (2 papers); chronic periodontitis (2); COVID-19 (2); gallbladder cancer (2); kidney disease (2); lung diseases (2); ovarian endometriosis (2); pancreatic adenocarcinoma (2); triple-negative breast carcinoma (2); alveolitis (1); Autoimmunity (1); bladder transitional cell carcinoma (1); chronic rhinosinusitis (1); clear-cell ovarian tumors (1); endocervical adenocarcinoma (1); familial breast cancer (1); gingivitis (1); head and neck cancer (1); Hernia (1); idiopathic pulmonary fibrosis (1); immune diseases (1); intraepithelial neoplasia (1); invasive ductal carcinoma of the breast (1); lung injury (1); metastatic tumours (1); myeloid leukemia (1); nasal polyps (1); Nephropathy (1); neuroblastoma (1); Obesity (1).
A further 11 diseases each share a sentence with SFN in 1 paper.